CDK6 (cyclin dependent kinase 6)
Diseases named in the same sentence as CDK6 in open-access papers (continued):
Sharing a sentence is not in itself a finding about the gene and the disease.
gastric cancer (75 papers, 2011 to 2025). A primary or metastatic malignant neoplasm involving the stomach. "For example, miR-129-2-3p has been demonstrated to facilitate the suppression of tumor growth in gastric cancer by targeting CDK6, a cell cycle-associated protein that plays a crucial role in the G1-S transition." (PMID 39440054, 2024). "CDK6 is overexpressed in stomach cancer tissues and is associated with poor survival from the disease." (PMID 36769170, 2023). "The upregulation of CDK6 in gastric cancer and its significant association with patient survival were illustrated by experiments or data mining, which was also in agreement with previous reports." (PMID 32310823, 2020). "It has been reported that the CDK6 protein is closely associated with the occurrence and development of gastric cancer." (PMID 25202363, 2014). "In the present study the association between miR-449a, the CDK6 protein and gastric carcinoma are identified." (PMID 25202363, 2014). "CDK6 encodes a cell cycle regulatory protein and is frequently amplified in gastric cancer." (PMID 28603669, 2017). "The result of the present study have validated the fact that the downregulation of miR-449a and the upregulation of CDK6 protein participate in the occurrence and development of gastric cancer, and have also added to the data on the association between miR-449a and the CDK6 protein." (PMID 25202363, 2014). "From this, it was indicated that miR-449a could regulate the expression of the CDK6 protein, and that this association may be closely correlated with the occurrence and development of gastric cancer." (PMID 25202363, 2014). "The association between the downregulation of miR-449a and the upregulation of CDK6 protein in gastric carcinoma was consequently identified, along with the association between the downregulation of miR-449a and the proliferation, apoptosis and migration of the gastric cancer MGC-803 cell line." (PMID 25202363, 2014). "Neferine inhibits the proliferation of gastric cancer cells by suppressing the expression of the cycling complex CDK4/CDK6/CyclinD1." (PMID 40138292, 2025). "CDK6 is an important factor that regulates the cell cycle, and overexpression or activation of CDK6 will accelerate the cell cycle and promote cell proliferation, thereby resulting in transformation and promoting gastric cancer occurrence and progression." (PMID 38711992, 2024). "For example, enhanced expression of miR-29a can inhibit mucin 1 (MUC1), reducing the expression levels of cell cycle-dependent kinases CDK2, CDK4, and CDK6, leading to reduced proliferation of gastric cancer cells." (PMID 39519347, 2024). "Considering the impact of LETM2 on cell cycle progression in gastric cancer, we conducted Western Blot experiments to evaluate the expression of G0/G1 phase-associated cyclins, CDK2, CDK4, CDK6, CyclinB1, and CyclinE2." (PMID 38654380, 2024). "Our findings demonstrated that CDKN2A VAR promoted cell proliferation by reducing expression of p16 with function as a regulator of the cell cycle of inhibiting CDK4 and CDK6 in gastric cancer." (PMID 38822443, 2024). "For example, lncRNA SUNO1 promotes cell cycle progression by controlling the YAP1/Hippo signaling pathway; miR-218 suppresses gastric cancer cell cycle progression via the CDK6/Cyclin D1/E2F1 axis." (PMID 37538116, 2023). "Another circular RNA circ_ASAP2 targeting miR-770-5p is upregulated in gastric cancer and leads to activation of CDK6, and has been termed as a potential target for gastric cancer therapy." (PMID 36769170, 2023). "Another circular RNA circZNF609 targeting miR-483 leads to the activation of CDK6 in gastric cancer cells to increase migration and proliferation." (PMID 36769170, 2023). "Another microRNA miR-29c that has been shown to be expressed to low extents in gastric cancer tissues and cells targets CDK6 directly, inhibiting its translation and subsequent activity in order to promote the development of gastric cancer." (PMID 36769170, 2023).
gastric cancer (continued). "The miR-191-5p targets mRNA of CDK6 coding mRNA at 5′UTR to inhibit the expression of CDK6 and its oncogenic functions in gastric cancer cells." (PMID 36769170, 2023). "CDK6 expression has been recorded to be higher in gastric cancer tissues than in normal gastric tissues." (PMID 36769170, 2023). "CDK4/6 inhibitor (PD-0332991) targeting CDK6 inhibited development or proliferation and induced apoptosis in stomach cancer cells." (PMID 36769170, 2023). "CDK6 is upregulated in gastric cancer and miR-107 regulates the levels of CDK6 as evidenced by the CDK6 3′UTR luciferase activity in gastric cancer cells." (PMID 36769170, 2023). "Cell division cycle 37 like 1 (CDC37L1) is downregulated in gastric cancer and inhibits CDK6, as demonstrated from the experiments showcasing that Palbociclib inversed the effects of CDC37L1 silenced gastric cancer cells." (PMID 36769170, 2023). "Another oncogenic long non-coding RNA LINC00974 upregulates CDK6 in gastric cancer cells and is involved in the regulation of cell cycle progression from G1 to S phase." (PMID 36769170, 2023). "Previous studies showed that UAP1L1 acted as a tumor promoter in the progression of gastric cancer by regulating the cell cycle regulator CDK6." (PMID 35168617, 2022). "It acted as a sponge of miR-483-3p, upregulated the expression of cell-promoting factor cyclin-dependent kinase 6 (CDK6), and promoted the proliferation and migration of gastric cancer cells through the circ-ZNF609/miR-483-3p/CDK6 axis." (PMID 35938040, 2022). "It has found that CDK6 positively regulates proliferation, migration and invasion of several cancer cells, such as esophageal cancer, gastric cancer and lung cancer." (PMID 33589577, 2021). "In gastric cancer, miR-218 was noted to inhibit cell cycle progression via the CDK6/CyclinD1/E2F1 axis." (PMID 34178650, 2021). "In this study, we demonstrated for the first time that CDC37L1 plays an inhibiting role in proliferation and migration through down-regulating CDK6 expression in gastric cancer." (PMID 33976724, 2021). "For instance, Xue et al22 reported that binding to hsa_circ_0081143 and miR646 effectively reversed the inhibition of CDK6, which was closely related to lymph node metastasis and was a poor prognosis predictor in patients with gastric carcinoma." (PMID 34152098, 2021). "In conclusion, this study revealed the abnormal overexpression of UAP1L1 and CDK6 in gastric cancer and the role of UAP1L1/CDK6 axis in gastric cancer progression." (PMID 32310823, 2020). "In gastric cancer, microRNA 378 affects cell proliferation and cell cycle by targeting CDK6 and VEGF genes." (PMID 32423014, 2020). "We next constructed SGC-7901 cells with mere UAP1L1 overexpression and simultaneous UAP1L1 overexpression + CDK6 knockdown to investigate the synergistic effects of them on gastric cancer." (PMID 32310823, 2020). "IHC analysis and TCGA data mining (P < 0.0001) were simultaneously performed to detect CDK6 expression in gastric cancer tissues and compared with that in normal tissues, both showing the upregulated expression of CDK6 in gastric cancer." (PMID 32310823, 2020). "In order to make clear the role of CDK6 in the development of gastric cancer, cytofunctional experiments were conducted using similar methods following the construction of CDK6 knockdown SGC-7901 cells." (PMID 32310823, 2020). "The prognosis information collected from 2055 gastric cancer patients in KM plotter database constructed the relationship between CDK6 high expression and relatively short survival period (P = 0.0088)." (PMID 32310823, 2020). "circ_0081143 was demonstrated to promote cisplatin resistance in gastric cancer cells through targeting miR-646/CDK6 pathway." (PMID 32855967, 2020). "In summary, CDK6 possessed similar regulatory effects on the development of gastric cancer with UAP1L1." (PMID 32310823, 2020).
gastric cancer (continued). "In this study, among the DEGs screened by a gene expression array, CDK6 was identified as a potential target of the UAP1L1 induced regulation of gastric cancer." (PMID 32310823, 2020). "Identified miR-29c targets include CDK6 in RCC2 in gastric carcinoma, TIAM1 in nasopharyngeal carcinomac and mantle cell lymphoma." (PMID 29262657, 2017). "The present study showed that there was downregulation of miR-449a and upregulation of the CDK6 protein in the clinical gastric cancer tissue samples." (PMID 25202363, 2014). "Quantitative (q)PCR and western blot analysis were used to analyze the expression of the miR-449a and the CDK6 protein in gastric carcinoma and tumor-adjacent normal tissues." (PMID 25202363, 2014). "An miR-449a expression group is also established in order to observe how miR-449a affects gastric carcinoma cells, and the ability of miR-449a to regulate the expression of the CDK6 protein is discussed." (PMID 25202363, 2014). "It was found that the expression of miR-449a was downregulated and the expression of CDK6 protein was upregulated in gastric carcinoma tissue." (PMID 25202363, 2014). "Downregulation of cell cycle proteins, including cyclin D1, CDK4 and CDK6, was also observed in metformin-treated gastric cancer cells." (PMID 24351837, 2013). "Alterations of CDK6 expression have been reported in several tumor types, including T-cell lymphoma, medulloblastoma, neuroblastoma, and gastric cancer." (PMID 23594394, 2013). "To clarify this issue, we analyzed the expression levels of RCC2, PPIC and CDK6 mRNAs in gastric carcinoma tissues and normal epithelial tissues using quantitative RT-PCR." (PMID 23442884, 2013). "Some studies have found that targeting CDK4/CDK6 can treat gastric cancer, and the main mechanism by which this approach exerts its effects is by impeding the cell cycle’s progression from the G1 phase to the S phase, thereby curbing the expansion and proliferation of malignant cells." (PMID 39879230, 2025). "The UDP-GlcNAc pyrophosphorylase-1 like 1 (UAP1L1) is another upstream driver of CDK6 in gastric cancer, as the phenotypes observed in UAP1L1 overexpressing cells were reversed in CDK6-silenced cells, suggesting that gastric cancer progression depends on CDK6 activity via multiple pathways." (PMID 36769170, 2023). "MiRNAs may regulate G1/S transitions by targeting important cell cycle regulators such as CDK1, CDK2, CDK4, and CDK6, as well as cyclin D1, D2, and E. MiR-195 binds to the 3′-UTR of CDK6 mRNA to negatively regulate CDK6 expression in gastric cancer." (PMID 37240281, 2023). "However, gastric cancer cells exhibit resistance to hyperthermia, and CDK6 is upregulated through the induction of AKT pathway inhibition and has been implicated as the protector of cells against apoptosis induced through hyperthermia." (PMID 36769170, 2023). "Therefore, CDK6 inhibition is considered a relevant option to overcome resistance to hyperthermia-related therapies for advanced gastric cancer." (PMID 36769170, 2023). "A circular RNA named hsa-circ-0081143, found in higher concentrations in gastric cancer, sponges miR-646 for its downregulation and induces the expression of CDK6, thus promoting cisplatin resistance in gastric cancer through regulation of the miR-646/CDK6 axis." (PMID 36769170, 2023). "Moreover, miR-449a is downregulated in gastric cancer and can target CDK6 in gastric cancer cells directly, as indicated in the gain of function experiments." (PMID 36769170, 2023). "MiR-1296-5p has been found to inhibit gastric cancer progression by suppressing CDK6 and EGFR." (PMID 35962353, 2022).
gastric cancer (continued). "Likewise, antisense noncoding RNA in the INK4 locus (ANRIL) enhances proliferation and tumorigenesis by epigenetically silencing miR-99a/miR-449a, and consequently upregulating mTOR and cyclin-dependent kinase 6 downstream pathways in gastric cancer." (PMID 33668685, 2021). "And CDK6 could be down-regulated by micro-RNAs, such as miR-129, miR-218, miR-449, to repress cell proliferation and migration in gastric cancer 31-33." (PMID 33976724, 2021). "MiR-218 could suppress gastric cancer cell cycle progression at G1 phase through CDK6/Cyclin D1/E2F1 axis in a feedback loop." (PMID 33330110, 2020). "In a word, these results clarified the promotion effects of UAP1L1 overexpression on gastric cancer, in which CDK6 may be involved." (PMID 32310823, 2020). "Also, another report presented that miR-29c retarded cell migration and invasion by inactivating cyclin-dependent kinase 6 (CDK6) in gastric cancer." (PMID 33251130, 2020). "Finally, similar with UAP1L1, the expression of CDK6 was found to be significantly higher in gastric cancer cells compared to GES-1 cells." (PMID 32310823, 2020). "Moreover, this study also aimed to explore the mechanism, by which UAP1L1 promotes the development and progression of gastric cancer, and identified CDK6 as a potential target of UAP1L1." (PMID 32310823, 2020). "Finally, correlation analysis revealed that FEZF1-AS1expression levels were positive correlation with SP1 and CDK2/CDK4/CDK6/CyclinD1 and inversely correlated with P21 expression levels in Gastric Cancer tissues." (PMID 28209170, 2017). "The present study identified that a lower expression level of miR-449 and a higher expression level of CDK6 may contribute to the occurrence and development of gastric cancer." (PMID 25202363, 2014). "Western blotting was also used to test the different expression levels of the CDK6 protein in the gastric carcinoma and tumor-adjacent normal tissues; the relative expression of the CDK6 protein was upregulated in the gastric carcinoma tissue compared with the tumor-adjacent normal tissue (P<0.001)." (PMID 25202363, 2014). "Therefore, we hypothesized that neferine could inhibit gastric cancer proliferation by suppressing the expression of the CDK4/CDK6/CyclinD1 complex." (PMID 40138292, 2025). "Further detection of the expression levels of CDK6 and Cyclin D1, which plays critical roles in cell cycle and is well known to be involved in the development of various types of human cancers including gastric cancer, showed downregulated expression induced by NDUFC1 knockdown." (PMID 34966665, 2021). "However, other studies demonstrated that miR-378 was down-regulated in gastric cancer and oral cancer, and miR-378 may act as tumor suppressors in gastric cancer by negatively regulating the expression of CDK6 and VEGF." (PMID 24555885, 2014). "Indeed, upregulation of CDK6 in gastric carcinoma has been reported by other research groups, and a portion of cases showing CDK6 overexpression harbored chromosomal amplification of 7q21.2, where the CDK6 gene is located." (PMID 23442884, 2013). "Moreover, 17 of the identified genes (CLDN4SRIMYCPRKDCSLPILAPTM4BMYBL2YWHABYWHAZMCM3SERPINE1SLC29A1ID1CDK6EIF2C2PTK2, and GSTA1) have previously been implicated in gastric cancer, and six of the genes (MYCSBDSCHCHD7TOP1COX6C, and CDK6) are included in the Cancer Gene Census." (PMID 22559327, 2012). "NCAPD3 loss can directly inhibit CCND1 and ESR1 expression to downregulate the expression of downstream targets CDK6 and IRS1 and inhibit the proliferation of gastric cancer cells." (PMID 38711992, 2024). "A long non-coding RNA, GHET1, is upregulated in gastric cancer, and its inhibition in gastric cancer cells leads to reductions in CDK2, Cyclin E1, CDK6, CDK4, and Cyclin D1." (PMID 36769170, 2023).
gastric cancer (continued). "Recent studies demonstrated that miR-218-5p served as a tumor suppressor to inhibit tumor growth and development by targeting endoplasmic reticulum oxidoreductase one alpha (ERO1A), COMMD8, CDK6, and EGFR in lung, liver, and gastric cancer." (PMID 36831545, 2023). "A tumor suppressor miRNA miR1296-5p in gastric cancer cells targets both EGFR and CDK6 for inhibition of growth, invasion, and migration, as observed in MGC-803 and SGC-7901 cell lines." (PMID 36769170, 2023). "miR-33a directly targeted cyclin-dependent kinases 6 (CDK6), cell cycle protein D1 (CCND1), and serine/threonine kinase PIM-1, and expression was down-regulated in gastric cancer tissues and cell lines, thereby inhibiting gastric cancer cell proliferation." (PMID 35743814, 2022). "We found that in gastric cancer cells CDK4, CDK6 and cyclinD1 were increased upon linc01133 overexpression." (PMID 35017464, 2022). "We showed that CDK6 and cyclin D protein levels were markedly downregulated in MICAL2-knockdown gastric cancer cells, whereas MICAL2 overexpression elicited the opposite effect." (PMID 34650666, 2021). "However, miR-33a could regulates CDK6 at both the mRNA and protein levels in gastric cancer cell." (PMID 33840361, 2021). "Previous studies showed that down-regulation of miR-33a promoted CDK6 and Proto-oncogene serine/threonine-protein kinase Pim-1 (PIM1) expression and induced gastric cancer cell proliferation, suggesting that miR-33a is a key regulator in cell proliferation." (PMID 32436962, 2020). "Expression of miR-646 has been shown to directly regulate CDK6 and FOXK1 expression in gastric cancer, suggesting its utility as a potential therapeutic target." (PMID 32344635, 2020). "Our results indicated a tumor-suppressive role of miR-1296-5p through the translational repression of oncogenic CDK6 and EGFR in gastric cancer." (PMID 30530570, 2019). "In gastric cancer cells, GAS5 was reported to inhibit proliferation by upregulation of p21 and suppression of CDK6." (PMID 29029523, 2017). "Decreased miR-29a-3p expression promoted gastric cancer cell proliferation via reducing the expression of cell-cycle regulators including: CDK2, CDK4, and CDK6." (PMID 25889078, 2015). "In multiple cases, miR-191 influences tumor progression by regulating proliferation; miR-191 promotes proliferation in hepatocellular carcinoma, and in gastric carcinoma by targeting NDST1, but inhibits proliferation in thyroid carcinoma by targeting CDK6." (PMID 25992613, 2015). "Prominent validated targets include CDK6, MYC, CCNE2, MET and GMNN and we furthermore validated the regulation of HDAC1 and SIRT1 also in gastric cancer cells." (PMID 21418558, 2011). "In addition, Piezo1 knockdown induced G1 phase block in gastric cancer cells and downregulated phosphorylated Rb, Cyclin D1, CDK4, and CDK6, suggesting that Piezo1 is required for gastric cancer cell proliferation." (PMID 38690080, 2024). "In summary, the NCAPD3 protein may target CCND1 or ESR1 to downregulate downstream factors such as CDK6 and IRSI to inhibit gastric cancer cell proliferation." (PMID 38711992, 2024). "More importantly, we found that knockdown of CDK6 could not only directly restrain the development of gastric cancer, but also alleviate even reverse the UAP1L1 overexpression induced promotion of gastric cancer." (PMID 32310823, 2020). "Park found that 19-nor-1,25-dihydroxyvitamin D2, a vitamin D analog, could block cell cycle of MKN45 gastric cancer cells by decreasing the expression of cyclin-dependent kinase(CDK), CDK2, CDK4, CDK6 and Cyclin D1." (PMID 28206978, 2017). "It was reported that miR145 induced by 1α, 25(OH)2D3 through VDR could inhibit colony formation, gastric cancer cell viability and induce cell arrest at S-phase by targeting E2F3 and CDK6." (PMID 28206978, 2017). "Interestingly, four of the identified key genes (CDK6, MCM2, PRKDC, and CCNE1) are on the cell cycle pathway, underscoring the importance of this process in gastric cancer." (PMID 28603669, 2017).